TIGIT (T cell immunoreceptor with Ig and ITIM domains)
Diseases named in the same sentence as TIGIT in open-access papers (continued):
Sharing a sentence is not in itself a finding about the gene and the disease.
tumor (continued). "Dual PD-1/TIGIT blockade increases tumor-specific CD8+ T cell expansion and function and promotes tumor rejection in mouse tumor models." (PMID 38890370, 2024). "Overwhelming evidence indicates that the combination of PD1 with HAVCR2, CTLA4 or TIGIT inhibitors can more effectively improve T-cell function and eliminate tumour cells." (PMID 38297380, 2024). "Co-inhibition of PD-L1 and TIGIT recovers cytotoxic T-cell activity and the suppression of tumour growth." (PMID 38893071, 2024). "Adding components to BiKE such as scFvs against KIRs, TIGIT, NKG2A and PD-1 receptors provides ability to circumvent inhibitory immune checkpoints therefore drives NK cell associated anti-tumor reactions." (PMID 38396050, 2024). "The T cell immunoglobulin and ITAM domain (TIGIT) is a recently discovered synergistic co-suppressor molecule that plays an important role in immune response and tumor immune escape in the context of cancer." (PMID 39113892, 2024). "TIGIT is extensively overexpressed on tumor-infiltrating lymphocytes (TILs) such as CD8+ T cells, CD4+ T cells, regulatory T cells (Tregs), and natural killer (NK) cells across various malignancies." (PMID 38229100, 2024). "The expression of TIGIT on tumor cells is particular to MCL, and when paired with targeted TIGIT, it can limit the recurrence of CAR T-cells." (PMID 38464517, 2024). "Given the interest in anti-TIGIT therapies in solid tumors, our purpose was to evaluate the degree of TIGIT expression on tumor-infiltrating T cells in RCC at different anatomic sites and relative to other cancer types." (PMID 39105820, 2024). "As such, TIGIT has been identified as a potential star immune checkpoint molecule that inhibits tumor growth and even helps to reduce resistance to immune checkpoint inhibitors in mouse models." (PMID 38229100, 2024). "As an immune checkpoint that inhibits activation of T cells and NK cells, TIGIT was first identified in 200921–23 and is involved in adaptive tumor immunological surveillance." (PMID 38724599, 2024). "The binding of PVRL2 to PVRIG or PVRL2 to TIGIT suppresses tumor immunity, whereas the binding of PVRL2 to DNAM1 promotes tumor immunity." (PMID 39156900, 2024). "TIGIT expression in humans is a late event in the cancer-immunity cycle, occurring after chronic exposure to tumor antigens." (PMID 38638433, 2024). "T-cell immunoreceptor with immunoglobulin and ITIM domain (TIGIT) is a co-inhibitory molecule expressed on T-cells, including tumour-infiltrating T-cells, Treg, memory subsets and NK cells." (PMID 38660136, 2024). "In cancer, TIGIT is expressed, together with PD-1, on tumor antigen-specific CD8+ T cells and on exhausted CD8+ T cell subsets and is associated with constant inflammatory responses." (PMID 38612483, 2024). "Contrary to LILRB1+ NK cells, the frequency of NK cells expressing T-cell immunoreceptor with Ig and ITIM domains (TIGIT), a critical inhibitory receptor correlated with NK cell exhaustion in host anti-tumor immunity, was decreased in ATB patients." (PMID 39030302, 2024). "Similar to the CD28/CTLA4 pathway, TIGIT/CD112 constitutes an emerging signaling pathway relating to the regulation of T cell immunity; indeed, a TIGIT blockade increases CD8+ T cell expansion against tumor antigens." (PMID 38612483, 2024). "The data likely indicates that the spleen is a sink for anti-TIGIT antibody, and blocking of TIGIT antigen in the spleen increases 89Zr-αTIGIT in circulation, allowing for the tracer to reach and accumulate within the tumor." (PMID 38438420, 2024). "Generally, the decreased TIGIT expression inhibited tumor growth in mice and activated IFN-γ secretion by NK and CD8+ T cells." (PMID 38229100, 2024). "Preclinical work validated the ability of anti-TIGIT mAbs to effectively inhibit T-cell proliferation and enhance the anti-tumor immune response, either as a standalone therapy or in conjunction with other immune checkpoint inhibitors." (PMID 38275876, 2024).
tumor (continued). "The findings indicate that in imatinib-resistant TME, tumor cells with activated immune and cytokine-mediated immune responses interacted with a higher proportion of Treg cells via the TIGIT-NECTIN2 axis." (PMID 38443340, 2024). "The presence of TIGIT expression in tumor-infiltrating lymphocytes (TILs) among melanoma patients is associated with tumor metastasis." (PMID 38216949, 2024). "In mice models and ongoing clinical research, blocking or ablating TIGIT, or blocking PD-1 alone or in combination, restores tumor inhibition." (PMID 35770416, 2023). "Supporting this finding, IF microscopy on primary tumour tissue revealed the presence of TIGIT-positive cells in both subtypes, while a consistently more prevalent staining pattern of NECTIN3 was observed in FP RMS." (PMID 37244912, 2023). "Mouse studies show that a combination of anti-PD-1 and anti-TIGIT markedly inhibits tumor growth, increases the ratio of cytotoxic T cells and regulatory T cells in tumors, and prolongs survival." (PMID 35770416, 2023). "A pivotal role in NK cell tumor immune surveillance is played by the DNAM-1/TIGIT/CD96/CD112R axis, a set of immunoglobulin immune receptors." (PMID 37760586, 2023). "As the TIGIT protein correlates with the degree of tumor differentiation and can be downregulated by RT, we believe that this probe can help indicate the regulation of the immune microenvironment of HCC by RT." (PMID 37124530, 2023). "PVR (CD115) and PVRL2 (CD112) bind to the TIGIT and are expressed on tumor, T, and antigen-presenting cells (APCs)." (PMID 36971124, 2023). "The dual blockade of PD-1/TIGIT increased the proliferation and function of tumor antigen-specific CD8+ T cells and TILs." (PMID 36980196, 2023). "TIGIT has also been described to interfere with the energy metabolism of T cells and thereby affect adaptive anti-tumor immunity." (PMID 36874131, 2023). "We also found the expression of TIGIT and its ligands on MDCSs in tumor tissue, suggesting the existence of further inhibitory mechanisms in NB." (PMID 37444427, 2023). "Tumor-infiltrating Tregs express high levels of cell surface molecules associated with T-cell activation, such as CTLA4, PD-1, LAG3, TIGIT, ICOS, and TNF receptor superfamily members including 4-1BB, OX40, and GITR." (PMID 37182149, 2023). "Similar increases in CD8+ T cell infiltration in 4T1 or CT26 tumor tissues were observed after OAd-Siglec10-Fc or OAd-TIGIT-Fc treatments." (PMID 38016957, 2023). "TIGIT can bind to two different ligands expressed by tumor cells and APCs: CD155 (PVR), and CD112 (PVR2) with lower affinity." (PMID 37056774, 2023). "Combining TIGIT blockade during tumor exposure with either PVR+ or PVR− restimulation allowed us to decern which function was negatively impacted by the engagement of the TIGIT/PVR pathway, and to what extent." (PMID 37345049, 2023). "TIGIT+ Tregs are highly suppressive and enriched in tumours and correlated with poor clinical outcome upon checkpoint blockade." (PMID 37325585, 2023). "In particular, the reversion of T cell exhaustion accompanied by a subsequent improvement in immune surveillance and tumor rejection was observed upon treatment with anti-TIGIT mAbs in combination with other ICI." (PMID 37629138, 2023). "As such, the low tumor uptake (0.629 ± 0.092%IA/g) of the Nb tracer 16988 is most likely correlated with the low levels of TIGIT expression on TILs within the MC38 tumor in our study." (PMID 37799715, 2023). "TIGIT was significantly upregulated in tumor tissue compared to adjacent normal tissue in the LUAD cohort." (PMID 37345049, 2023). "In vitro, antibody blockade of PVR or PVRL2 on HCC cell lines or TIGIT blockade on immune cells increased immune cell-mediated lysis of tumour cell." (PMID 37383234, 2023). "In vitro activated PIT coexpressed PD-1, LAG-3 and TIGIT but were highly cytotoxic against autologous tumor and uniquely secreted cytokines and chemokines in the > 100 pM range." (PMID 37063842, 2023).
tumor (continued). "We also identify a putative interaction between NECTIN3 and TIGIT, specific to the more aggressive fusion-positive (FP) RMS subtype, as a potential cause of tumour-induced T-cell dysfunction." (PMID 37244912, 2023). "The low molecular weight D-peptide TBP-3 that targets TIGIT was reported to penetrate and accumulate in the tumor tissues." (PMID 37129788, 2023). "TIGIT is highly expressed on activated NK cells and correlates with higher anti-tumor function, although during prolonged tumor exposure, its engagement can result in a decrease in NK cell function." (PMID 37345049, 2023). "We also assessed the CD96-associated TIGIT marker, which was found to be involved in the immunosuppression of CD155 on NK cells in tumour tissue." (PMID 37760110, 2023). "Studies on oral microbiota also present a dual perspective: The Fap2 protein, expressed by F. nucleatum, interacts with human inhibitory receptors TIGIT to facilitate the evasion of tumor cells from NK cells and T cells." (PMID 37954233, 2023). "TIM-3, TIGIT, and 2B4 are co-expressed on T cells in tumor tissue and peripheral blood from multiple types of cancer." (PMID 36913701, 2023). "Especially in tumour tissues, the interaction of TIGIT with CD155 has been applied to clinical tumour treatment." (PMID 37760110, 2023). "PD-1, CTLA4, CD96, and TIGIT are important immune checkpoints that are potential targets for tumor immunotherapy." (PMID 36936375, 2023). "TIGIT expression was upregulated in tumor-bearing mice, and aconite (all doses) significantly increased its expression." (PMID 36756040, 2023). "By transplanting the variable domains of this anti-TIGIT mAb onto various antibody backbones, we show that a functionally intact Fc backbone is required for the antitumor activity of the anti-TIGIT mAb across several syngeneic murine tumor models." (PMID 38022590, 2023). "An analysis of tumor tissue revealed both TIGIT and TIGIT ligand expression on myeloid-derived suppressor cells (MDSCs), suggesting additional mechanisms of protumoral effects in NB." (PMID 37444427, 2023). "Although ADCC by DB resulted in a strong activation of NK cells leading to an effective tumor cell lysis, a remarkable induction of PD-L1 expression on NB cells, and of TIGIT and PD-1 on effector cells, especially on NK cells, was observed." (PMID 37444427, 2023). "With this in mind, we sought to understand the mechanisms of RT plus anti-TIGIT combination therapy using a mouse tumor model." (PMID 35794399, 2023). "TIGIT+ NK cells had enhanced cytotoxic function, resulting in a greater level of degranulation and effector cytokine secretion after exposure to tumor targets, suggesting that TIGIT is a marker of NK cell activation." (PMID 37345049, 2023). "In murine models, TIGIT+ NK cells recovered from either spleen or tumors of tumor-bearing mice had a lower frequency of IFNγ-, TNFα-, or DNAM-expressing cells as compared to TIGIT− NK cells." (PMID 37345049, 2023). "This represented an important cellular mediator of response to TIGIT inhibition that can generate an inflammatory anti-tumor TME." (PMID 38008725, 2023). "Combination blockade of TIGIT improved the tumor growth control induced by RT+ARTi therapy in the MOC2 model and thus can be considered a novel strategy to improve therapeutic effects." (PMID 37208386, 2023). "The study shows how Fusobacterium nucleatum binds to tumor cell surfaces, facilitating its interaction with the inhibitory receptor TIGIT of NK cells through its Fap2 protein." (PMID 37887550, 2023). "The specificity of this interaction was due to the significantly higher expression of NECTIN3 in FP tumour cells, while the expression of TIGIT in Tregs and CD8 + T cells was comparable between subtypes." (PMID 37244912, 2023). "More TIGIT+ NK cells expressed major activating receptors and exerted anti-tumor response as compared to TIGIT− cells, indicating that NK cells with greater anti-tumor function express more TIGIT." (PMID 37345049, 2023).
tumor (continued). "Regarding NK cells, the selective TIGIT blockade was sufficient to impair tumor growth, demonstrating a pivotal role for NK cell-mediated tumor rejection upon anti-TIGIT therapies." (PMID 37629138, 2023). "Our study first described the expression of the exhaustion markers TOX and TIGIT in the mucosa and tumor of patients with CAC." (PMID 37835436, 2023). "Blocking TIGIT has been shown to enhance NK cell cytotoxicity and slow tumor growth in a mouse model of melanoma." (PMID 38057843, 2023). "As LAG-3, TIM3, BTLA, and TIGIT belong to the co-inhibitory receptors, which are known to impair anti-tumor immunity." (PMID 37946136, 2023). "It was observed that RT and the anti-TIGIT antibody synergistically enhanced the accumulation of tumor-infiltrating DCs, which activated CD8 + T cells." (PMID 35794399, 2023). "The use of Flt3L to increase CD103 + DCs at the tumor site has the potential to improve clinical response to RT and anti-TIGIT treatment in cancer patients." (PMID 35794399, 2023). "In OC model mice, blocking TIGIT significantly reduced tumor growth and the proportion of CD4+ Tregs and increased the survival rate." (PMID 37670328, 2023). "PD-1 and TIGIT ligands are expressed widely within the tumor bed but combined PD-1 and TIGIT checkpoint blockade can significantly overcome the immunosuppressive effect of PD-1 and TIGIT engagement on T-cell function." (PMID 36689623, 2023). "Several clinical trials have been established to evaluate anti-LAG-3, anti-TIM-3, or anti-TIGIT mAbs as different tumor therapies." (PMID 37670328, 2023). "As the result of various mechanisms (including the inhibition of T cell priming), TIGIT inhibits both T cells and NK cells, leading to an impaired anti-tumor immune response and making it an interesting factor in the context of cancer immunotherapy." (PMID 36980196, 2023). "The immune checkpoints PD1, PD-L1, CTLA-4, and TIGIT play instrumental roles in tumor immune escape." (PMID 36637946, 2023). "Blockade of the T cell immunoreceptor with the immunoglobulin and immunoreceptor tyrosine-based inhibitory motif domain (TIGIT) can enhance innate and adaptive tumor immunity and radiotherapy (RT) can enhance anti-tumor immunity." (PMID 35794399, 2023). "The expression levels of immune checkpoint genes, including CTLA4, CD96, and TIGIT, were also enriched in the first layer (0–250 μm) on the tumor side, indicating an elevated immunosuppressive status of immune cells in this area." (PMID 37337030, 2023). "After injection of a combination of the anti-PD-1 antibody and anti-TIGIT antibody, there was evidence of reduced tumor growth, increased overall survival, and more expression of CTLs." (PMID 37999131, 2023). "Taken together, these results corroborate the importance of the in vitro findings and show that there is a correlation between levels of activated NK cells, TIGIT tumor tissue expression, and better outcomes." (PMID 37345049, 2023). "Previous studies have shown that PVR molecules expressed on the surface of tumor cells can bind to TIGIT on the surface of NK cells, which lead to inhibitory signals in NK cells, and then reduce the function of NK cells to kill tumor cells." (PMID 37035135, 2023). "TIGIT competitively binds CD155/CD112 on the APC/tumor cells which exerts immunosuppressive effects on CD8+T cells that are highly expressed the multiple IRs, eventually resulting in the formation of exhausted T cells that have lost their tumor-killing effect." (PMID 37106742, 2023). "LUAD-TCGA database analysis demonstrated that TIGIT expression in the tumor tissue positively correlated with activating NK cells, while the presence of activating NK cells correlated with better outcomes." (PMID 37345049, 2023). "In mice with a heavy tumor burden, blockade of the TIGIT pathway prevented NK cell exhaustion and promoted NK-cell-dependent tumor immunity." (PMID 36765704, 2023).
tumor (continued). "Once CD155, which is highly expressed on tumor surface, binds to TIGIT on NK and T cells surface, its killing effect on tumor cells is inhibited." (PMID 37359558, 2023). "Similar to GC, higher infiltration levels of exhausted TIGIT+CD8+ T cells are observed in CRC tumor tissues with low levels of killer cytokines, including IFN-γ, IL-2, and TNF-α, but higher inhibitory receptors expression, such as PD-1, LAG-3, and TIM-3." (PMID 37180158, 2023). "RT plus anti-TIGIT blockade led to a statistically significant increase in the total number of DCs present in tumor tissues and TdLNs." (PMID 35794399, 2023). "Studies have found that TIGIT expression is elevated in ccRCC tumors and that blocking TIGIT can enhance the anti-tumor immune response." (PMID 37175653, 2023). "As expected, we detected a clear expression of CD155 on tumor cells and of TIGIT on NK cells infiltrating tumor tissue." (PMID 37444427, 2023). "TIGIT expressed by tumor cells and antigen-presenting cells in the TME is critical in limiting innate and adaptive immunity against tumors." (PMID 37161430, 2023). "In mouse models, blockade of TIGIT restored NK cell cytotoxicity, increased IFNγ and TNFα expression, and promoted tumor-specific T cell immunity." (PMID 37345049, 2023). "To investigate the contribution of CD103 + DCs toward the effects of combination therapy, we compared MC38 tumor growth upon TIGIT blockade plus RT in WT or BATF3−/− mice, which lack CD103 + CD8 + DCs." (PMID 35794399, 2023). "The first mechanism investigated was ADCC because TIGIT expression within the tumor bed is primarily on immunosuppressive Tregs and dysfunctional CD8+ T cells." (PMID 38022590, 2023). "More importantly, it not only plays a significant inhibitory role in CD8+ T cells, but TIGIT was also found combating anti-tumor immunity by influencing nature kill cells, antigen-presenting dendritic cells, and T regulatory cells (Tregs)." (PMID 37035135, 2023). "Given the expansion of PD-1+TIGIT+ T cells on TIL, we next determined the expression of the ligands for PD-1 and TIGIT on cell populations within the tumor microenvironment." (PMID 36689623, 2023). "Altogether, these observations from functional and transcriptomic analyses demonstrated that TIGIT blockade restored PM21-NK cell anti-tumor functions against PVR+ cancer cells after exposure to cancer cell spheroids." (PMID 37345049, 2023). "In the future, NOTA conjugated TIGIT single domain antibody would be used to monitor tumor TIGIT expression, and human TIGIT would be explored for further study." (PMID 37129788, 2023). "A strong inhibition of tumor growth was observed between days 11 and 16, and between days 12 and 15, for the “DB + anti-PD-L1” and “DB + anti-TIGIT” experimental groups, respectively." (PMID 37444427, 2023). "A recent study found that TIGIT is elevated on surfaces of tumor infiltrating lymphocytes and that CD155 is elevated on cancer cell surfaces." (PMID 35770416, 2023). "Studies of TIGIT in NK cells can better show the important role of TIGIT in inhibiting anti-tumor immunity." (PMID 37035135, 2023). "Immune Checkpoints are expressed by different cell types such as T cells (PD1, TIGIT), macrophages, dendritic cells, and tumor cells (PDL1 and IDO2)." (PMID 38260202, 2023). "Innate ICIs achieve anti-tumor purposes by targeting checkpoints such as SIRPα, TIGIT, PVRIG, LILRB2, NKG2A, LAG-3, TIM-3, VISTA and CD32B." (PMID 37510993, 2023). "ADCC by DB resulted in a strong tumor cell lysis but induced the expression of PD-L1 and TIGIT on effector cells including NK cells." (PMID 37444427, 2023). "Blocking or deleting TIGIT has been shown to promote NK cell-mediated antitumor responses and reduce the metastatic potential of tumor cells." (PMID 35770416, 2023). "A polyclonal anti-TIGIT antibody enhanced NK cell-mediated killing of tumor cells in vitro, demonstrating that TIGIT inhibition has the potential to improve NK cell anti-tumor functions." (PMID 37760586, 2023).